IL6 (interleukin 6)
Diseases named in the same sentence as IL6 in open-access papers (continued):
Sharing a sentence is not in itself a finding about the gene and the disease.
periodontal disease (continued). "Potential biological pathways through which periodontal diseases can negatively affect human milk composition include the systemic dissemination of inflammatory cytokines like IL-6, PGE2, and tumor necrosis factor (TNF)-β that can be up-regulated by bacterial by-products." (PMID 39540631, 2024). "The improvement in BOP may be due to RSV’s anti-inflammatory effect, which reduces the release of proinflammatory cytokines (IL-1, IL-6, and TNF-α) implicated in the pathophysiology of periodontal disorders." (PMID 41328922, 2024). "Inflammatory mediators, such as Interleukin 6 (IL-6) and Interleukin 8 (IL-8), along with total salivary proteins, are gaining attention as salivary biomarkers because they are closely related to the progression of periodontal disease." (PMID 39917715, 2024). "First, periodontal disease‐induced systemic inflammation may result in the production of peripheral proinflammatory cytokines, such as C‐reactive protein, IL‐1, IL‐6, and tumor necrosis factor‐alpha." (PMID 38648391, 2024). "Moreover, a negative correlation between miR-23a-3p and TNFα (r = -0.891, p < 0.01) and IL-6 (r = − 0.503, p < 0.05) was observed in the early stage of periodontal disease." (PMID 36599866, 2023). "Thus, the aim of this study was to explore for the first time the involvement of miR-15a-5p, miR-23a-3p, miR223-3p, miR-103a-3p, miR-423-5p and TNFα, IL-6 production in periodontal disease pathological and healthy GCF." (PMID 36599866, 2023). "On a more detailed level, there is evidence that periodontal disease could increase circulating levels of certain pro-inflammatory cytokines, including IL-6, IL-1β, and TNF-α, that were also found to be upregulated in serum samples of men with prostatitis." (PMID 37046667, 2023). "Moreover, OSA have been shown to alter the tested bacteria in plaque, and OSA correlated with increasing periodontal disease severity, and had an additive effect on salivary IL-6." (PMID 37233636, 2023). "For instance, in pregnant women with periodontal disease, inflammatory cytokines, such as interleukin-1β (IL-1β), interleukin-6 (IL-6), and prostaglandin E2 (PGE2), which are produced by stimulated periodontal tissue, reach the placenta and fetus through blood flow." (PMID 36163018, 2022). "It plays a paramount role in periodontal disease and alveolar bone destruction by producing proinflammatory mediators such as IL-1β, IL-6, and TNF-α, which are multifunctional cytokines produced by lymphocytes, monocytes, and fibroblasts with extensive biological activities." (PMID 35911651, 2022). "Accordingly, there may be a link between the IL-6 levels and clinical parameters of periodontal disease." (PMID 35268009, 2022). "The presence of local cancer or periodontal disease induced a higher PB level of IL-6, which may influence the general health of patients or may be associated with the development/progression of other diseases." (PMID 35804048, 2022). "Moreover, numerous studies have reported a positive relationship of periodontal disease morbidity with inflammatory cytokines, including tumor necrosis factor, interleukin (IL)-1, IL-6, and IL-8, which are involved in arteriosclerosis." (PMID 34262126, 2021). "Significantly higher levels of IL-1β, IL-6, IL-8, and IL-10 were found in constipated subjects with GB from this study, indicating an ongoing inflammatory process and the progression of periodontal disease." (PMID 33717115, 2021). "Local expression of tumour necrosis factor (TNF), interleukin-1β (IL-1β), and IL-6 due to inflammation triggered by bacteria involved in periodontal disease might promote and exacerbate ASCVD." (PMID 34911523, 2021). "Previous studies have shown elevated serum levels of IL-6 in patients with periodontal disease." (PMID 33327639, 2020).
periodontal disease (continued). "Therefore, the presented results need to be confirmed by further studies, which including assessment of hand dexterity, dental caries, periodontal diseases and inflammation cytokines such as IL-6 and TNF-alpha." (PMID 32649678, 2020). "Periodontal disease, with its local and systemic bacterial load, can also trigger a systemic inflammatory response with increased inflammatory cytokines (TNF-α, IL-1, and IL-6) and inflammatory mediators (PGE2) to become a risk factor of preterm delivery." (PMID 30154640, 2018). "Furthermore, C. rectus LPS also induces higher levels of IL-6 and prostaglandin E2 productions in aged human gingival fibroblasts as compared with those in younger cells, which may explain the increased susceptibility of periodontal disease in aged individuals." (PMID 30087857, 2018). "Therefore, the objective of this work was to analyze the cytokines IL-2, IL-6, IL-10, and TNF-α and inflammatory mediators such as PGE2 in pregnant patients at risk of preterm delivery and their relationships with periodontal disease." (PMID 30154640, 2018). "IL-6 is a multifunctional cytokine, as it can be both proinflammatory and anti-inflammatory, and its secretion is thought to drive the tissue damaging process in diseases such as periodontal disease." (PMID 30087857, 2018). "IL-33 exacerbates periodontal disease, increases IL-6 expression, and enhances a Th17 response." (PMID 28320468, 2017). "Studies confirm that certain salivary biomarkers, i.e. IFN-γ, IL-1-β1, TNF-α, IL-6, IL-4 and IL-8, may be used for predicting future development of periodontal diseases." (PMID 25976216, 2015). "The higher expression levels of IL-6 in untreated periodontal disease might induce an increase in matrix metalloproteinases (MMPs) that are related to tissue destruction." (PMID 26479870, 2015). "In further research, other systemic markers that might be more specific to periodontal disease such as fibrinogen, leptin, white blood cell count, and interleukin-6 should be considered." (PMID 26346216, 2015). "In periodontal diseases, inflammatory mediators, including interleukin (IL)-6, IL-8 and tumor necrosis factor-α (TNF-α), may promote the degeneration of inflamed periodontal tissues." (PMID 24137277, 2013). "Moreover, previous data obtained using a reverse transcription polymerase chain reaction (RT-PCR) and ELISA showed that the mRNA expression, as well as protein expression, of IL-6 was increased in patients with periodontal diseases." (PMID 24137277, 2013). "Similarly, other authors demonstrated a trend to increased IL-6 levels in diabetic subjects with periodontal disease." (PMID 22611374, 2012). "Results obtained in this study indicate that increased concentrations of salivary IL-1β and IL-6, rather than being caused by local inflammation, periodontal disease and smoking, reflect local production of these cytokines in cancer tissue." (PMID 21743397, 2012). "Therefore, treating periodontal disease not only reduces pro-inflammatory mediators such as IL-6, tumor necrosis factor-α (TNF-α), CRP, and reactive oxygen species (ROS), but also increases the levels of pro-resolving lipid mediators, which are crucial for maintaining homeostasis." (PMID 40916006, 2025). "Furthermore, factors such as radiotherapy, vitamin C application and tocilizumab application, as well as monoclonal antibodies, might have the ability to elevate or depress IL-6 levels, which are in direct correlation with periodontal diseases." (PMID 38396821, 2024). "Additionally, inflammatory cytokines, such as MMP-9, TNF-a, and IL-6, which are increased in periodontal disease, could potentially impact lung health through aspiration." (PMID 38909262, 2024). "Moreover, IL-6 is associated with alveolar bone resorption, and IL-8 with its effect on neutrophils, investigation of IL-6 and IL-8 expression in patients with periodontal disease may be used as an indicator of treatment response." (PMID 39548434, 2024).
periodontal disease (continued). "In conclusion, our study has demonstrated that salivary levels of IL-6, IL-8, and total protein significantly vary among patient groups with differing periodontal conditions, affirming the discriminative potential of these biomarkers in distinguishing between healthy states and periodontal disease." (PMID 39917715, 2024). "Moreover, IL-10 has been shown to inhibit IL-6 production by human gingival fibroblasts exposed to bacterial LPS, supporting the idea that this factor decreases inflammation in connective tissues in periodontal disease." (PMID 37508659, 2023). "In patients with periodontal disease, the degree and frequency of endotoxemia is increased with the severity of the disease, which contributes to systemic inflammation, including increased blood levels of C‐reactive protein, IL‐6, and tumor necrosis factor alpha." (PMID 34463983, 2021). "Additionally, periodontal disease treatments reduce the levels of IL-6, CRP, etc.33–36." (PMID 34262126, 2021). "Studies concerning oral diseases, such as periodontal diseases, lichen planus or oral carcinoma, demonstrated the increased salivary levels of selected pro-inflammatory nuclear factor-κB dependent cytokines, e.g., interleukin 1β (IL-1β), interleukin 6 (IL-6), tumour necrosis factor α (TNF-α)." (PMID 33050496, 2020). "Pro-inflammatory cytokines such as IL-1β, IL-6, and TNF-α produced by monocytes, macrophages, and fibroblasts stimulated by pathogenic factors of periodontal pathogens contribute to the progress the periodontal disease as well as systemic diseases such as diabetes and rheumatoid arthritis." (PMID 30574217, 2018). "Furthermore, the model presented may elucidate important CHD biomarkers which should be measured in patients with periodontal disease to more adequately screen for CHD risk, namely HOMA, TNF-α, CRP, IL-6, GDF-15, OPG, MPO and fibrinogen." (PMID 27846870, 2016). "In conclusion, the Kampo formulation Rokumigan, through suppression of biofilm formation by F. nucleatum, inhibition of IL-6 secretion by gingival epithelial cells and fibroblasts, and promotion of wound healing in a fibroblast model, may have potential application for periodontal diseases." (PMID 24877093, 2014). "IL-6 levels may correlate with the severity of periodontal disease." (PMID 20407653, 2009). "High levels of interleukin-1 (IL-1), interleukin-6 (IL-6), prostaglandin E2 (PGE2), and TNF-α have been detected in the gingiva and gingival crevicular fluid (GCF) of patients with periodontal disease." (PMID 40323540, 2026). "Periodontal disease involves the chronic production of inflammatory cytokines, such as TNF-α, IL-1β, IL-6, IL-8, and IL-17, which contribute to the destruction of soft and hard tissues." (PMID 40867800, 2025). "Several pro-inflammatory interleukins, notably IL-1β, IL-6, TNF-α, and IL-17, have been proposed as biomarkers for periodontal disease." (PMID 41155385, 2025). "The authors investigated the role of MMP-8, 9, IL-1β, IL-6, and TNF-α along with MIP-1α and found that MIP-1α had the highest discriminatory role in periodontal disease among adults." (PMID 38433948, 2024). "Pro-inflammatory cytokines, like interleukin-1β (IL-1β) and interleukin-6 (IL-6), in GCF can be reliable indicators of periodontal disease progression due to their high sensitivity in detecting inflammatory changes in periodontal tissues." (PMID 39795606, 2024). "Interleukin-6 (IL-6) was selected for analysis because it interacts with ACE2 regulators, contributes to the development of periodontal disease, and maintains periodontal tissue homeostasis by coordinating the host response." (PMID 39917640, 2024). "Cytokines such as IL-1β, TNF-α, IL-6, and RANKL are pivotal in managing the immune response in periodontal diseases." (PMID 38595889, 2024).
periodontal disease (continued). "Numerous pieces of research have shown that inflammatory cytokines like tumor necrosis factor alpha (TNF-α), C-reactive protein (CRP), and interleukin-6 play a role in the connection between PCOS and periodontal disorders." (PMID 38021744, 2023). "These salivary cytokines, particularly IL-1β, IL-6, and TNF-α, offer reliability in assessing the severity of periodontal disease, making them valuable markers for monitoring disease progression." (PMID 38192959, 2023). "(i) If IL-1β, IL-6, AND TNF-α are elevated in the serum of patients with periodontal disease OR COVID-19 infection." (PMID 37106750, 2023). "Pro-inflammatory cytokines and chemokines, comprising IL-1 β, IL-6, and TNF-α, create an environment that fosters periodontal disease progression by affecting the balance in chronic inflammation." (PMID 34460002, 2022). "Proinflammatory mediators expressed in the rheumatoid synovium such as IL-6, TNF-α, transglutaminase 2, and inflammasome Nlrp3 have also been detected in saliva and serve as biomarkers for periodontal disease." (PMID 36506787, 2022). "Similar inflammatory mediators, such as IL-6, TNF- α, and CRP, are increased in patients with severe periodontal disease (PD)." (PMID 36361416, 2022). "RA and periodontal disease share many similarities in etiology and pathogenesis, and both are characterized by excessive production of inflammatory cytokines such as TNF and IL-6." (PMID 36294882, 2022). "A recent systematic review reported that the combination of MIP-1α, IL-1β, IL-6, and MMP-8 was acceptable as biomarkers for diagnosing periodontal disease." (PMID 34199256, 2021). "Pro-inflammatory cytokines, IL-1β, IL-6, TNF-α, and IFN-γ, have a major role in the pathogenesis of periodontal disease and were also detected in healthy GCF samples." (PMID 35048035, 2021). "Inflammatory cytokine biomarkers, such as interleukin-1 beta (IL-1β), interleukin-6 (IL-6), and tumor necrosis factor alpha (TNF-α) are significantly elevated in patients with cardiovascular and periodontal disease." (PMID 34299815, 2021). "The inflammatory response was assessed by measuring the production of IL-6,- IL-8, and MCP-1, which are involved in the progression of periodontal disease." (PMID 32295577, 2020). "Another study demonstrated that the increased IL-6, IL-1β and MCP-1 mRNA levels were observed in a mouse model of experimental periodontal disease, and this was suppressed by an Am80 treatment." (PMID 32651445, 2020). "In humans, concentrations of IL-1, IL-6 and TNF-α in the gingival crevicular fluid are known to contribute to acute and chronic inflammation in periodontal disease." (PMID 30822336, 2019). "The concentration of pro-inflammatory cytokines such as IL-6 and TNF-α in gingival crevicular fluid (GCF) increases with the progress of periodontal disease." (PMID 30574217, 2018). "The levels of inflammatory mediators (IL-1β, IL-6, β-glucuronidase, and TNF-α) in saliva and in serum (except IL-6) significantly increased with severity of periodontal disease." (PMID 29017560, 2017). "We focused on the measurements on the expression of IL-6, CXCL8, and CCL2, which are thought to play an important role in the progression of periodontal disease." (PMID 27504628, 2016). "The study found depressed women to have significantly higher levels of periodontal disease and GCF IL-6 after adjusting for age and smoking." (PMID 26751953, 2016). "Patients with periodontal disease had significantly higher serum CRP, IL-6 and TNF-α values by comparison with healthy subjects." (PMID 26644840, 2015). "After a 20 days of daily local melatonin application in such diabetic patients with periodontal disease, a significant decrease in serum CRP and IL-6 levels as well as an improvement in the gingival index and pocket depth was observed." (PMID 26644840, 2015). "To summarize, the diabetic patients with periodontal disease had significantly higher serum CRP, IL-6 and TNF-α values by comparison with healthy subjects." (PMID 26644840, 2015).
periodontal disease (continued). "Before melatonin treatment, serum TNF-α, IL-6 and CRP levels in diabetic patients with periodontal disease were significantly higher than in healthy control subjects." (PMID 26644840, 2015). "We focused on the measurements of the expression of IL-6, IL-8, and MCP-1, which are produced by periodontal ligament cells and are thought to play an important role in the progression of periodontal disease." (PMID 24587317, 2014). "A number of inflammatory mediators, such as interleukin (IL)-1, IL-6, IL-8, tumor necrosis factor-α (TNF-α), prostaglandins and matrix metalloproteinases (MMPs) are involved in periodontal diseases." (PMID 24137277, 2013). "Therefore, IL-6 levels may correlate less with periodontal disease than CRP or orosomucoid." (PMID 23526947, 2013). "Anticytokine therapy for periodontal diseases mainly targets TNF-α, IL-1β, and IL-6, because they are essential for the initiation of inflammatory immune reactions and are produced for prolonged periods in inflammatory disease." (PMID 20407652, 2009). "High amounts of TNF- α, IL-1, IL-6, and PGE2 have been detected in the GCF of patients with periodontal disease, indicating that local inflammatory cytokines also play an active role in periodontal disease-related pathologies." (PMID 40323540, 2026). "In addition, elevated levels of salivary IL-1β, IL-6, and TNF-α reflect activation of the local inflammatory response, which is consistent with previous studies on salivary biomarkers in periodontal disease." (PMID 41301927, 2025). "Periodontal diseases contribute to systemic health issues by triggering chronic inflammation, as evidenced by elevated levels of biomarkers like C-reactive protein (CRP), interleukin-6 (IL-6), and tumor necrosis factor-alpha (TNF-α)." (PMID 40418274, 2025). "On the other hand, inflammatory cytokines generated during periodontal disease, such as TNF-α and interleukins (IL-1, IL-6), could penetrate the systemic circulation and exacerbate the inflammatory condition linked to OSA." (PMID 39061956, 2024). "Evaluation of the quantitative IL-6 values in patients with and without periodontal diseases clearly illustrates the close connection of this pro-inflammatory cytokine and pathological processes related to the periodontium." (PMID 38396821, 2024). "Inflammatory Markers: Periodontal disease can lead to elevated levels of systemic inflammatory markers such as C-reactive protein (CRP), tumor necrosis factor-alpha (TNF-α), and various interleukins (IL-1, IL-6, IL-8)." (PMID 39610974, 2024). "In addition, pre-inflammation cytokines, including IL-6, IL-17, IFN-γ, TNF-α, and other inflammatory molecules, were reported to elevate in the serum of periodontal disease patients." (PMID 37181367, 2023). "Salivary cytokines, particularly IL-1β, IL-6, and TNF-α, can serve as reliable markers for periodontal disease severity and may aid in monitoring disease progression." (PMID 38192959, 2023). "A lack of correlation between IL-6 concentration in saliva and the presence of periodontal diseases has been already demonstrated." (PMID 35054284, 2022). "Excessive pro-inflammatory cytokines and some inflammatory mediators were found in periodontal disease including TNF-α, IL-6, and IFN-γ could quantify the acute or chronic inflammatory responses after the administrations of MitoQ@PssL NPs." (PMID 36588945, 2022). "A previous study revealed that A. dahurica blocks excessive proinflammatory cytokines, such as interleukin-1β (IL-1β), interleukin-6 (IL-6), and interferon-γ (IFN-γ) to provide protective effects against periodontal diseases to alleviate inflammatory responses." (PMID 34234674, 2021). "Although differences in TNF-α and TNF-β were not correlated with the periodontal disease treatment outcome, differences in IL-1α, IL-1β, IL-6, and IL-8 were significantly higher in the ET group in this study." (PMID 25884025, 2015).